FRAT2 (FRAT regulator of Wnt signaling pathway 2)
Description:
Positively regulates the Wnt signaling pathway by stabilizing beta-catenin through the association with GSK-3.
Synonyms: FRAT-2
Tractability: PROTAC: ubiquitination databases record sites on it.
Gene: Protein-coding gene on chromosome 10 (97,332,497 to 97,334,729, reverse strand). Ensembl gene ENSG00000181274.
Subcellular location (Human Protein Atlas): Nucleoplasm; Mitochondria
Pathways (Reactome):
Signal Transduction: Beta-catenin phosphorylation cascade; Disassembly of the destruction complex and recruitment of AXIN to the membrane
Gene Ontology:
Cellular component: cytoplasm; cytosol
Genetic constraint (gnomAD): Loss-of-function variants: 0 observed, 0.21 expected, observed/expected ratio (o/e) 0, 90% interval 0 to 1.88. That is too few expected variants to judge how well the gene tolerates losing a copy. Missense variants: 325 observed, 219.43 expected, observed/expected ratio (o/e) 1.48, 90% interval 1.35 to 1.62. Synonymous variants: 204 observed, 112.57 expected, observed/expected ratio (o/e) 1.81, 90% interval 1.61 to 1.97.
Homologues: Orthologues: chimpanzee FRAT2 (99% identical), macaque FRAT2 (97% identical). Paralogues in human: FRAT1 (80% identical).
Diseases named in the same sentence as FRAT2 in open-access papers:
FRAT2 is named in the same sentence as 15 diseases in open-access papers, as found by Europe PMC text mining. Sharing a sentence is not in itself a finding about the gene and the disease. The quoted sentences say what the papers report.
gastric cancer (2 papers, 2012 to 2022). A primary or metastatic malignant neoplasm involving the stomach. "The up-regulation of the FRAT2 gene has been reported in human gastric cancer and has been implicated in carcinogenesis through activation of the Wnt signaling pathway." (PMID 22691236, 2012).
prostate carcinoma (2 papers, 2020 to 2022). A carcinoma that arises from epithelial cells of the prostate gland. "Frat1 demonstrates oncogenic properties in prostate cancer by inhibiting GSK 3β against β-catenin and thus promoting cell growth, while Frat2 mediates the oncogenic activation of Rac by mixed lineage leukemia fusions." (PMID 32212785, 2020).
breast carcinoma (1 paper, 2022). "The FRAT1 and FRAT2 genes are clustered in the human chromosome locus 10q24.1, and both genes have been previously identified as proto-oncogenes in a variety of tumours, including basal-like breast cancer, ovarian cancer, and GC." (PMID 36153370, 2022).
cervical cancer (1 paper, 2020). A primary or metastatic malignant neoplasm involving the cervix. "Pearson correlation analysis displayed that the expression of FRAT1 and FRAT2 were both positively associated with the expression of DANCR in cervical cancer tissues." (PMID 32123519, 2020). "Both public available TCGA data and cervical cancer tissues we collected display that the expression of FRAT1 and FRAT2 are positively associated with the expression of DANCR in cervical cancer tissues, supporting the positive regulation of FRAT1 and FRAT2 by DANCR." (PMID 32123519, 2020). "DANCR promotes cervical cancer growth via activating FRAT1/FRAT2-Wnt/β-catenin signaling pathway." (PMID 32123519, 2020). "In this study, we identified a novel mechanism mediating the oncogenic roles of DANCR in cervical cancer, which is the activation of the Wnt/β-catenin signalling pathway via upregulation of FRAT1 and FRAT2." (PMID 32123519, 2020). "Our results displayed that enhanced expression of DANCR upregulated the mRNA and protein expression levels of FRAT1 and FRAT2, and while knockdown of DANCR downregulated the mRNA and protein expression levels of FRAT1 and FRAT2 in cervical cancer cells." (PMID 32123519, 2020).
lung carcinoma (1 paper, 2012). "Interestingly, in relation to clinical pathological parameters of Asian lung cancer patients, mRNA overexpression of ARHGAP19 and FRAT2 was significantly associated with lung SCC." (PMID 22691236, 2012). "The mean gene dosage of lung cancer candidate genes ARHGAP19, FRAT2, PAFAH1B1, and ZNF322A in tumor tissues was significantly higher than the corresponding normal tissues in Asian lung cancer." (PMID 22691236, 2012).
pancreatic cancer (1 paper, 2024). "MiR-29c down-expresses during pancreatic cancer and directly modulates WNT upstream regulators, including FRAT regulator of WNT signaling pathway 2 (FRAT2), frizzled cass receptor 5 (FZD5), lipoprotein receptor-related protein 6 (LRP-6) and frizzled class receptor 4 (FZD4)." (PMID 38559560, 2024).
parathyroid carcinoma (1 paper, 2023). "Other mutations in KMT2D, KRAS (in-frame deletion), and FRAT2 (FRAT regulator of WNT signaling pathway 2) are potentially associated with the oncogenesis of parathyroid carcinoma; however, the evidence remains limited." (PMID 37121965, 2023).
tumor (10 papers, 2011 to 2024). "The expression of several race-associated genes was also dependent on the MED12 mutation status of the tumor, being higher (FRAT2, TNFRSF19, ACP7, IRS4, PLEKHG4B, KRT17, SLN, and ZNF703) or lower (CAV2) in the mutated specimens compared with wild-type tumors." (PMID 37686244, 2023). "For instance, in cells overexpressing miR–221, we observed an upregulation of FRAT2, AMD1, and MTHFD1L, genes linked to tumor progression, severity, invasiveness, and worse prognosis." (PMID 38339342, 2024). "FRAT1 and FRAT2 are tumor promoting genes whereas VANGL1 is a tumor suppressor gene which involved in the Wnt/ß-catenin signaling pathway and thus posses as a molecular target of nobiletin." (PMID 32212785, 2020). "Fourth, FRAT1 synergises with FRAT2 to promote tumour metastasis in vitro and in vivo." (PMID 36153370, 2022). "To address the functional consequences of FRAT1 cooperating with FRAT2 on tumour metastasis, we inoculated MKN45 cells transduced with Lv-vector, Lv-FRAT1, Lv-shRNA, Lv-FRAT2 shRNA2, or Lv-FRAT1 + FRAT2 shRNA2 into BALB/c-nu/nu mice." (PMID 36153370, 2022). "Cluster I consisted of genes upregulated in CC cells, which included tumor-related genes such as LGR4, AGR2, PCAF, TMEM97, FRAT2, EFNB2 and ZIC2." (PMID 21333016, 2011).
cancer (2 papers, 2020 to 2022). A tumor composed of atypical neoplastic, often pleomorphic cells that invade other tissues. "The FRAT1 and FRAT2 genes, which are cancer-associated genes, are clustered in the human chromosome at the 10q24 locus." (PMID 36153370, 2022). "Most patients exhibited lower miR-3648 levels but higher FRAT1 and FRAT2 protein levels in cancer tissues (T) compared to normal gastric mucosa (N)." (PMID 36153370, 2022). "FRAT1 and FRAT2 are important effectors of some miRNAs in human cancers; therefore, there is a need to further explore the biological effects of miR-3648 on FRAT1 and FRAT2." (PMID 36153370, 2022). "Among the genes positively associated with DANCR, we noted FRAT1 and FRAT2, which are positive regulator of the Wnt/β-catenin signaling pathway and have oncogenic roles in several cancers." (PMID 32123519, 2020). "Previous reports showed that FRAT1 or FRAT2 is related to cancer cell invasion and motility." (PMID 36153370, 2022).
neurodegenerative disease (1 paper, 2021). A disorder of the central nervous system characterized by gradual and progressive loss of neural tissue and neurologic function. "In B cells, the upregulated genes KIR3DL2, QPCT, and PPP2R2B are all involved in neural function and neurodegenerative diseases, and the downregulated genes FRAT2 and WWC3 are involved in the Wnt/β-Catenin signaling pathway, which is associated with AD pathogenesis." (PMID 34880454, 2021). "In addition, differentially expressed genes in B cells were identified; both the upregulated genes (KIR3DL2, QPCT, PPP2R2B) and the downregulated genes (FRAT2, WWC3, SPG20) had certain connections with neurodegenerative diseases." (PMID 34880454, 2021).
neurological diseases (1 paper, 2023). "Among the top 50 database-predicted targeted genes, 8 genes (HOMER1, FRAT2, GRM5, TGFBR1, KDM3A, RGS2, ARRB1, and YWHAZ) were reported to be associated with axonal/neuronal regeneration/or neurological diseases." (PMID 36959678, 2023).
FRAT2 also shares sentences with these, for which no sentence is quoted: leiomyoma (1 paper); leukemia (1); ovarian carcinoma (1); T cell lymphomas (1).